NLRP3 (NLR family pyrin domain containing 3)
Diseases named in the same sentence as NLRP3 in open-access papers (continued):
Sharing a sentence is not in itself a finding about the gene and the disease.
diabetic nephropathy (continued). "Furthermore, increased in renal biopsies of people with diabetic nephropathy, NLRP3 and IL1β expression and activity is also reportedly increased in people with tubulointerstitial injury as compared to those without." (PMID 35755447, 2022). "Enhanced NLRP3 expression was detected in murine cultured podocytes, and human kidneys with mild signs of diabetic nephropathy exhibited immunohistochemical staining for NLRP3 in proximal and distal tubules as well as in sporadic cells that appeared to be podocytes." (PMID 33494430, 2021). "In addition, the NLRP3 inflammasome involvement has been described in other forms of kidney disease, including crystalline nephropathies, diabetic nephropathy, IgA nephropathy as well as lupus nephritis." (PMID 34680443, 2021). "Studies have shown that NLRP3 activation can exacerbate diabetic nephropathy in diabetic mice." (PMID 34712322, 2021). "In the mouse model with NLRP3 knockout diabetic nephropathy, renal inflammation and fibrosis can be partially suppressed, suggesting that the pro-inflammatory effect of the NLRP3 inflammasome may promote renal fibrosis." (PMID 35185542, 2021). "Under the regulation of NOX4, TXNIP may inhibit the activation of NLRP3 inflammatory bodies by dissociating from Trx and binding with NLRP3, and PU may play a meaningful role in protection against diabetic nephropathy." (PMID 32456088, 2020). "In NLRP3-deficient mice, reduction of pro-inflammatory cytokines is associated with reduction of pro-inflammatory factor MCP-1 and macrophage infiltration, which protected from development of high fat diet-induced obesity and diabetic nephropathy." (PMID 32660446, 2020). "NLRP3 plays an important role in the inflammation cascade by amplifying an inflammation response; thus, inhibition of NLRP3 inflammasome activity has been proposed as a strategy for treating various diseases, including neurological diseases, osteoarthritis, diabetic nephropathy, liver fibrosis." (PMID 33424842, 2020). "The expression of NLRP3 was confirmed in both tubular cells and podocytes, and it was increased in biopsies of human kidney diseases (hypertension kidney injury, acute tubular necrosis, diabetic nephropathy, IgAN, and lupus nephritis)." (PMID 31427885, 2019). "Our previous study had demonstrated that IL-22 could alleviate renal lesion and fibrosis in diabetic kidney disease through suppression of NLRP3 inflammasome activation." (PMID 31616439, 2019). "NLRP3, IL-1β, and IL-18 in rats with diabetic nephropathy were markedly increased." (PMID 30555415, 2018). "Studies identified that inhibiting NLRP3 inflammasome activation could ameliorate diabetic cardiomyopathy, diabetic retinopathy, diabetic nephropathy, and diabetic vascular endothelial dysfunction." (PMID 29495433, 2018). "BSA was shown to induce the activation of the NLRP3 inflammasome in diabetic nephropathy." (PMID 29914975, 2018). "ROS-induced TXNIP overexpression could drive hepatic inflammation as well as lipid accumulation, diabetic retinopathy and diabetic nephropathy through activation of NLRP3 Inflammasome." (PMID 29084550, 2017). "Our results firstly reveal that high glucose and lipopolysaccharide activate ROS/TXNIP/ NLRP3/IL-1β inflammasome signaling in glomerular mesangial cells, suggesting a mechanism by which inflammation may contribute to the development of diabetic nephropathy." (PMID 26881256, 2016). "Likewise, mitochondrial ROS and NLRP3 inflammasome activation aggravate diabetic nephropathy in non myeloid-derived cells." (PMID 25798846, 2015). "In addition, a recent study revealed that the suppression of toll-like receptor 9 gene expression in diabetic nephropathy mice can also effectively inhibit the activation of NF-κB and NLRP3 inflammasome pathways, thereby reducing the expression of inflammatory and apoptotic factors." (PMID 40841164, 2025).
diabetic nephropathy (continued). "Hence, future therapeutic strategies aimed at modulating exosomal contents could offer a novel approach to mitigating renal pathological changes by inhibiting NLRP3 inflammasome activation in diabetic nephropathy." (PMID 39104818, 2024). "Hence, the repression of NLRP3 inflammasome contributes to the function of coptisine on diabetic nephropathy, maybe through interacting with caspase-1 directly or modulating the Nrf2 or NF-κB pathways indirectly." (PMID 37197172, 2023). "High glucose often plays a key role in the development of diabetic nephropathy, and a growing body of evidence suggests that dysregulation of NLRP3 activation may play a role in the progress of diabetic nephropathy via regulation of inflammatory response and RIF44,45." (PMID 37872392, 2023). "Therefore, targeting the NLRP3 inflammasome might be an effective strategy for regulating inflammation and fibrosis in diabetic kidney disease." (PMID 37237918, 2023). "Thus, we speculated that the NF-κB pathway may also attribute to NLRP3 inflammasome suppression by coptisine in diabetic nephropathy." (PMID 37197172, 2023). "Hence, indicating that targeting NLRP3 inflammasome in diabetes could act on Mφ in diabetic nephropathy." (PMID 32316547, 2020). "Moreover, our recent study has demonstrated that IL-22 could ameliorate renal lesion and fibrosis in diabetic kidney disease by suppression of renal NLRP3 inflammasome activation." (PMID 31616439, 2019). "The dysfunction of NLRP3 inflammasome has been increasingly be reported to participate in the development and progression of a series of kidney diseases, including acute kidney injury, chronic kidney disease, diabetic nephropathy, as well as autoimmune kidney disease." (PMID 31616439, 2019). "Therefore, systemic activation of the NLRP3 inflammasome might play an essential role in the development and progression of diabetic nephropathy." (PMID 31694192, 2019). "Inflammation is a key driver of diabetic kidney disease (DKD) progression, with the NOD-like receptor family pyrin domain-containing 3 (NLRP3) inflammasome representing a promising therapeutic target." (PMID 42131331, 2026). "In diabetic nephropathy models, both in vivo and in vitro, MCC950 attenuates glomerular basement membrane thickening, podocyte injury, and renal fibrosis by suppressing the NLRP3/caspase-1/IL-1β signaling axis." (PMID 41357229, 2025). "In immortalized mouse podocytes, high glucose can induce podocyte pyroptosis by up-regulating NLRP3, ASC, caspase-1, and GSDMD(N), while in the kidneys of diabetic nephropathy mice, markers of pyroptosis are also significantly increased." (PMID 39850113, 2025). "Beyond enhancing NLRP3 expression through FcγRs/NF-κB signaling, CRP promotes diabetic nephropathy progression through Smad3-mediated activation of NLRP3 inflammasomes." (PMID 41377556, 2025). "(+)-Catechin also suppresses NLRP3-associated inflammation in the kidney, as demonstrated by reductions in NLRP3, ASC, AIM2, caspase 1, IL-1β, and IL-18 expression in mice with diabetic nephropathy and palmitic acid-treated HK-2 cells." (PMID 41020857, 2025). "In this study, our objective was to explore the effects of EGCG on podocytes and in diabetic kidney disease (DKD) mice and investigate how EGCG modulates the TXNIP/NLRP3/IL‐1β signaling pathway in DKD, both in podocytes and animal models." (PMID 39723074, 2024). "Piperine and its derivatives significantly alleviate the conditions of diabetic nephropathy by decreasing the signaling of TNF-α, NLRP3 inflammasome, NF-κB, and IL-1β in a diabetic rat model." (PMID 38200253, 2024). "Recent studies have demonstrated that Astragaloside IV (AS-IV) can suppress the expression of NLRP3, Caspase-1, GSDMD, IL-1β, and IL-18, thereby mitigating podocyte cell death in diabetic nephropathy (DN)." (PMID 39104818, 2024).
diabetic nephropathy (continued). "In patients with diabetic nephropathy (DN), WTAP is highly expressed, and WTAP knockdown inhibits the m6A methylation of NLRP3 mRNA to downregulate NLRP3 inflammasome activation, which further induces cell pyroptosis and inflammation." (PMID 37063421, 2023). "For instance, it was reported that AMPK activation can suppress NLRP3 overactivity and decrease inflammatory cytokines such as IL1β, IL6, IL18, and TNF-α in a mouse model of diabetic nephropathy." (PMID 36818747, 2023). "Recent studies have shown that SNHG16 exacerbates diabetic nephropathy by stabilizing TLR4 to regulate RAS and NF-κB pathway-mediated NLRP3 inflammatory vesicle activation." (PMID 37280692, 2023). "Some of the latest cell studies also inhibit podocyte pyroptosis by interfering NLRP3 inflammasome signaling pathway, such as using the NLRP3 inflammasome inhibitor MCC950, which is expected to be used in treating diabetic nephropathy." (PMID 36387904, 2022). "In our previous studies, we found that Syk/JNK activated the NLRP3 inflammasome in diabetic cardiomyopathy (DCM) and diabetic nephropathy (DN)." (PMID 34603335, 2021). "Hyperglycemia plays a vital role in diabetic nephropathy (DN); autophagy and its potential upregulator receptor-interacting protein kinase 2 (RIPK2) are associated with ROS, which play a potential role in regulating NLRP3, and may be involved in inflammation in DN." (PMID 31485193, 2019). "Previous studies reported NLRP3 complex was involved in the progression of kidney diseases in UUO model,ischemia/reperfusion injury (IRI), and diabetic nephropathy etc. and traditional Chinese herbs had obvious inhibition on it." (PMID 31118021, 2019). "However, the role of the NLRP3 inflammasome in diabetic nephropathy remains unclear." (PMID 26881256, 2016). "Inhibiting oxidative stress and inflammatory reactions associated with apoptosis, significantly reduceing levels of Caspase-1, IL-1β, and NLRP3 and improving GBM thickening and inflammatory cell infiltration, thereby suppressing the development of diabetic nephropathy." (PMID 40568564, 2025). "BPS can improve renal injury and renal fibrosis in db/db diabetic nephropathy mice, which may be related to the decrease of apoptosis, inhibition of inflammation, reduction of ECM, and regulation of NLRP3 inflammasome." (PMID 41394140, 2025). "Recent studies highlight NLRP3 inflammasome, PPAR subtypes, and JAK/STAT signaling as key therapeutic targets, given their critical roles in regulating inflammation, autophagy, EMT, and fibrosis in diabetic nephropathy." (PMID 41415561, 2025). "The progression of diabetic nephropathy is driven by multiple molecular mechanisms, including TGF-β1/Smads, NF-κB, MAPK, PI3K/AKT, NLRP3 inflammasome, peroxisome proliferator-activated receptors (PPARs), JAK/STAT, and sodium-glucose cotransporter-2 (SGLT2) pathways." (PMID 41415561, 2025). "Research has indicated that the NLRP3 inflammasome plays a pivotal role in the development of ED24 and that inhibiting the NLRP3 inflammasome-mediated NF-κB signaling pathway can significantly attenuate the inflammatory response in diabetic nephropathy." (PMID 41090037, 2025). "NLRP3 also strengthens other inflammatory pathways, such as NF-κB signaling pathway and mitogen-activated protein kinase (MAPK) signaling pathway, and augments oxidative stress and inflammation in diabetic nephropathy." (PMID 36818747, 2023). "By blocking the NLRP3/caspase-1/IL-1 pathway and lowering urinary NGAL levels in mice with a model of diabetic nephropathy, researchers demonstrated that MCC950 might significantly alleviate diabetic chronic kidney injury." (PMID 38114914, 2023). "The activation of the TLR4/NF-κB signaling pathway could modulate NLRP3 inflammasome activation in inflammatory bowel disease and induce GSDMD-mediated pyroptosis in tubular cells in diabetic kidney disease." (PMID 34646128, 2021).
diabetic nephropathy (continued). "Double immunofluorescence staining also revealed that NLRP3 was markedly upregulated in E-cadherin-negative tubules from several CKD including diabetic nephropathy (DN), IgA nephropathy (IgAN), and lupus nephritis (LN)." (PMID 34716316, 2021). "In this study, we investigated the intervention effect of PU on diabetic nephropathy in a mice model induced by high-fat diet and STZ to prove the protective effect of PU on diabetic nephropathy and explore the possible mediating role taken by the TXNIP/NLRP3 pathway in the pyroptosis mechanism." (PMID 32456088, 2020). "In the Tokushima rat model, activation of NLRP3 inflammasomes accelerates macrophage recruitment and M1 polarization, promoting CXCL12 and high mobility group box-1 release in the proximal tubule, and contributing to the progression of diabetic nephropathy." (PMID 32660446, 2020). "The NLRP3 inflammasome is activated in various kidney diseases both acute and chronic kidney disease, such as ischemic-reperfusion injury (IRI), crystal-induced fibrosis and diabetic nephropathy." (PMID 30483252, 2018). "It was reported that the lncRNA NEAT1/miR-34c/NLRP3 axis regulates pyroptosis activation and that the lncRNA MEG3/miR-181a/Egr-1/TLR4 signaling pathway promotes fibrosis and the inflammatory response, both of which mediate the progression of diabetic nephropathy." (PMID 34941711, 2021). "However, diabetic nephropathy was improved in WT bone marrow transplanted-NLRP3 KO mice but not in NLRP3 KO bone marrow transplanted-WT mice." (PMID 31694192, 2019). "This suggested that NLRP3 in nonimmune renal cells could be critical for aggravating diabetic nephropathy." (PMID 31694192, 2019). "However, the role and mechanism of NLRP3 inflammasome in diabetic nephropathy is not yet fully understood." (PMID 26881256, 2016). "Similarly, in diabetic nephropathy, the total flavones of Abelmoschus manihot (TFA) inhibit the pyroptosis of podocytes under high glucose conditions by regulating METTL3-dependent m6A modification and inhibiting the activation of the NLRP3 inflammasome and PTEN/PI3K/Akt signaling." (PMID 37063421, 2023).
Hyperglycemia (215 papers, 2012 to 2026). An increased concentration of glucose in the blood. "In diabetic conditions, hyperglycemia acts as a damage-associated molecular pattern (DAMP) that directly activates NLRP3, leading to IL-1β maturation and subsequent insulin resistance and β-cell dysfunction." (PMID 40943351, 2025). "Clinical and experimental data further show that risk factors such as hyperglycaemia markedly potentiate NLRP3 inflammasome activity, exacerbating ischemic injury and promoting HT." (PMID 41408503, 2025). "Numerous studies have demonstrated that the NLRP3 inflammasome plays an important role in the pathogenesis of various diseases, NLRP3 inflammasome retina caused by early hyperglycemia, and affecting the structure and function of the blood-retinal barrier." (PMID 38243268, 2024). "Reactive oxygen species (ROS) and hyperglycemia activate NLRP3 oligomerization and the associated inflammatory programmed cell death, which can progress to DC." (PMID 37056985, 2023). "During the development of DCM, excessive hyperglycemia can cause an increase in reactive oxygen species, which activate NF-κB and subsequently trigger the activation of NLRP3, driving cellular inflammation and apoptosis." (PMID 36506810, 2022). "Risk factors such as oxidative stress, hyperglycemia, dyslipidemia, inflammation, mitochondrial dysfunction, and endoplasmic reticulum stress can activate the NLRP3 inflammasome." (PMID 36006939, 2022). "In diabetic atherosclerosis, the activation and regulation of NLRP3 inflammasome are affected by damage-associated molecular patterns (DAMPs), including hyperglycemia, hyperlipidemia, and urate crystals." (PMID 35692570, 2022). "Hyperglycemia can cause NLRP3 to recruit ASC and bind to pro-caspase-1 to form an inflammasome and activate caspase-1." (PMID 36425593, 2022). "For example, HIF-1α-mediated regulation of the NLRP3/IL-1β signalling pathway has been reported to play a role in susceptibility to pulmonary aspergillosis in a hyperglycaemia mouse model." (PMID 36275017, 2022). "In summary, our data suggest that UCP2 deficiency enhances NLRP3 inflammasome activation and ROS production after neurons in hyperglycemia-exacerbated cerebral I/R damage in vivo and in vitro." (PMID 33735403, 2021). "UCP2 deficiency further increased the expression of NLRP3 and cleaved caspase 1 in neurons in the context of hyperglycemia-exacerbated cerebral I/R damage." (PMID 33735403, 2021). "We evaluated the effects of UCP2 deficiency and the activation of the NLRP3 inflammasome in hyperglycemia-induced exacerbation of cerebral ischemic injury." (PMID 33735403, 2021). "In this study, we found that UCP2 deficiency exacerbated NLRP3 inflammasome activation and increased ROS production in neurons after hyperglycemia-exacerbated cerebral I/R damage in vivo and in vitro." (PMID 33735403, 2021). "The accumulation of reactive oxygen species (ROS) in individuals with DKD caused by hyperglycemia is an important activator of the NLRP3 (NOD-like receptor family, pyrin domain containing 3) inflammasome." (PMID 34506229, 2021). "Taken together, the present study suggests that UCP2 deficiency enhances NLRP3 inflammasome activation by increasing ROS production in the context of hyperglycemia-exacerbated I/R damage." (PMID 33735403, 2021). "Previous studies have shown that the NLRP3 inflammasome is related to the destruction of endothelial cell connections caused by hyperglycaemia, leading to hyperglycaemic complications." (PMID 34180143, 2021). "Especially, hyperglycemia causes hyper-inflammation through activation of NLRP3 inflammasome, which can lead to cell apoptosis, hypertrophy, and fibrosis." (PMID 32471242, 2020). "Similar to previous studies, hyperglycemia caused NLRP3 inflammasome activation in HT22 hippocampal cells." (PMID 29507694, 2018).